IFT81 (intraflagellar transport 81)
Description:
Component of the intraflagellar transport (IFT) complex B: together with IFT74, forms a tubulin-binding module that specifically mediates transport of tubulin within the cilium. Binds tubulin via its CH (calponin-homology)-like region. Required for ciliogenesis. Required for proper regulation of SHH signaling. Plays an important role during spermatogenesis by modulating the assembly and elongation of the sperm flagella (By similarity).
Synonyms: CDV-1; CDV1; CDV-1R; MGC4027; CDV1R; DV1; SRTD19
Tractability: PROTAC: ubiquitination databases record sites on it; its protein half-life has been measured.
Gene: Protein-coding gene on chromosome 12 (110,124,335 to 110,218,795, forward strand). Ensembl gene ENSG00000122970.
Subcellular location: Cell projection, cilium; Cytoplasm; Cytoplasm, cytoskeleton, cilium basal body
Subcellular location (Human Protein Atlas): Cytosol; Basal body; Centrosome; Primary cilium
Pathways (Reactome):
Organelle biogenesis and maintenance: Intraflagellar transport
Gene Ontology:
Molecular function: protein binding; tubulin binding
Biological process: cilium assembly; intraciliary transport involved in cilium assembly; regulation of smoothened signaling pathway; intraciliary anterograde transport; intraciliary transport; sperm flagellum assembly; spermatogenesis; microtubule-based movement
Cellular component: ciliary basal body; intraciliary transport particle A; intraciliary transport particle B; ciliary tip; cilium; cytoplasm; motile cilium; centriole; centrosome; intraciliary transport particle; microtubule organizing center; sperm midpiece; sperm principal piece
Genetic constraint (gnomAD): Loss-of-function variants: 25 observed, 33.11 expected, observed/expected ratio (o/e) 0.75, 90% interval 0.55 to 1.05. The upper end of that interval is the gene's LOEUF score, 1.05, which puts it in group 4 of 6, group 1 being the genes least tolerant of losing a copy. Missense variants: 319 observed, 361.3 expected, observed/expected ratio (o/e) 0.88, 90% interval 0.81 to 0.97. Synonymous variants: 106 observed, 108.66 expected, observed/expected ratio (o/e) 0.98, 90% interval 0.83 to 1.15.
Gene-disease validity (ClinGen):
ClinGen rates the evidence that IFT81 causes each of these diseases.
short-rib thoracic dysplasia 19 with or without polydactyly (autosomal recessive): Moderate.
Homologues: Orthologues: chimpanzee IFT81 (99% identical), macaque IFT81 (98% identical), rabbit IFT81 (95% identical), pig IFT81 (93% identical), mouse Ift81 (93% identical), rat Ift81 (93% identical), guinea pig IFT81 (88% identical), tropical clawed frog ift81 (77% identical), zebrafish ift81 (70% identical), Caenorhabditis elegans ift-81 (26% identical).
Diseases named in the same sentence as IFT81 in open-access papers:
IFT81 is named in the same sentence as 35 diseases in open-access papers, as found by Europe PMC text mining. Sharing a sentence is not in itself a finding about the gene and the disease. The quoted sentences say what the papers report.
ciliopathies (6 papers, 2015 to 2025). "This work describes identification of mutations of IFT81 in individuals with symptoms consistent with the clinical spectrum of ciliopathies." (PMID 26275418, 2015). "Here, we report the identification of human mutations of IFT81 in two unrelated individuals with multisystemic symptoms consistent with ciliopathy phenotypes." (PMID 26275418, 2015). "In summary, we here identify mutations in IFT81 and suggest that they represent an exceedingly rare cause of a ciliopathy phenotype in humans." (PMID 26275418, 2015). "IFT81, a core component of the IFT-B complex, involved in the bidirectional transport of ciliary proteins, has been recently implicated in syndromic ciliopathies." (PMID 28460050, 2017). "IFT81 is involved in the intraflagellar transport and thus contributes to the ciliogenesis which may also participate to the restoration of the well-formed axonemes after gene transfer treatment as previously observed in another ciliopathy model." (PMID 38504136, 2024). "In the light of the known clinical overlap between different ciliopathies and their genetic heterogeneity and pleiotropy, it is not surprising that disease-causing variants in ITF74 as well as in IFT81 can lead to similar features." (PMID 33875766, 2021).
Intellectual disability (3 papers, 2015 to 2021). "As a result, in an individual with retinal dystrophy and intellectual disability (NCK033), we found a homozygous deletion of five nucleotides in IFT81 resulting in a loss-of-stop codon and extension of the predicted protein by 10 amino acids (c.2015_2019del (p.Asp672Alafs*15))." (PMID 26275418, 2015).
nephronophthisis (3 papers, 2015 to 2018). Progressive tubulointerstitial injury, inherited in an autosomal recessive pattern, caused by mutations in genes involved in ciliary function, which may result in an end stage renal failure. "Mutations of IFT81 in humans lead to multiple symptoms that include polydactyly, nephronophthisis, asphyxiating thoracic dystrophy, short rib polydactyly and retinal dystrophy." (PMID 29514868, 2018). "Consequently, we identified a homozygous mutation in IFT81 affecting an obligatory donor splice site in an individual with nephronophthisis and polydactyly." (PMID 26275418, 2015).
Retinal dystrophy (3 papers, 2015 to 2018). Retinal dystrophy is an abnormality of the retina associated with a hereditary process. "With exception of this caveat, given the functional evidence presented along with a lack of other potentially explanatory mutations, the c.1841T>C mutation in IFT81 is the likely candidate for inherited retinal dystrophy in this proband." (PMID 28460050, 2017). "This proband presented with retinal dystrophy and brain lesions including cerebellar atrophy, a phenotype to which the IFT81 variant might contribute." (PMID 26275418, 2015). "In conclusion, our findings highlight IFT81 as a candidate for inherited retinal dystrophy, thereby implying the importance of a core IFT-B protein, IFT81, in the human retina." (PMID 28460050, 2017).
male infertility (2 papers, 2022 to 2023). The inability of the male to effect fertilization of an ovum after a specified period of unprotected intercourse. "Mutations in other IFT-B gene additional to IFT74 (IFT81, IFT20, IFT27, IFT172), and in IFT-A genes (IFT140) can cause spermatogenesis defects and male infertility in mice." (PMID 37555648, 2023). "Additionally, deficiency in IFT74, IFT81, IFT140, and IFT172 have been proven to be related to spermiogenesis defects and male infertility." (PMID 36321563, 2022).
retinal degeneration (2 papers, 2017 to 2022). Degeneration of the retina. "A variety of genes involved in IFT, such as Ift88, Ift122, Ift81, Ift172, and Ift52, have been reported to be associated with retinal degeneration." (PMID 36171205, 2022).
breast carcinoma (1 paper, 2021). "However, the expression of IFT52 and IFT81 was upregulated in the breast cancer cells, and the expression of IFT88 showed an undetectable difference between HBL-100 and MCF-7 cells." (PMID 33748116, 2021).
melanoma (1 paper, 2024). A malignant, usually aggressive tumor composed of atypical, neoplastic melanocytes. "In TvHdb RVYLDIVTPK (IFT81) was identified exclusively in melanoma samples (in 17 of 31 HLA-A*03:01/A*11:01/A*31:01-positive tumor metastases or patient-derived cell lines) and RLSSSLPSR (ST3GAL6) was identified in melanoma (in 9 of 31 HLA-A*03:01/A*11:01/A*31:01-positive melanoma samples)." (PMID 39835134, 2024).
retinitis pigmentosa 1 (1 paper, 2025). Any retinitis pigmentosa in which the cause of the disease is a mutation in the RP1 gene. "Similarly, rhodopsin is mislocalised in Rp1−/− mouse photoreceptors, mutations in RP1 cause Retinitis Pigmentosa 1, and IFT81 has been reported as candidate gene for non-syndromic retinal dystrophy." (PMID 39934925, 2025).
situs inversus (1 paper, 2023). A congenital condition in which there is complete right-to-left reversal of the position of the major thoracic and abdominal organs (that is, they are arranged in a mirror image of the normal positioning). "Situs inversus defects can occur in humans with IFT81 mutations and are found in mouse IFT-A mutants." (PMID 37555648, 2023).
tumor (2 papers, 2021 to 2024). "To collect further evidence for the tumor specificity of the two cryptic peptides RVYLDIVTPK (IFT81) and RLSSSLPSR (ST3GAL6), we evaluated their immunogenicity applying an in vitro priming assay." (PMID 39835134, 2024).
retinopathy (1 paper, 2017). "In this report, we identified mutations in IFT81 as candidates for a recessive form of nonsyndromic retinopathy." (PMID 28460050, 2017). "Therefore, our finding provides the first report linking the core IFT-B protein, IFT81, to nonsyndromic retinopathy." (PMID 28460050, 2017).
IFT81 also shares sentences with these, for which no sentence is quoted: infection (4 papers); Cerebellar atrophy (2); polydactyly (2); asphyxiating thoracic dystrophy (1); Bardet-Biedl syndrome (1); Blindness (1); colon cancer (1); cystic kidney disease (1); dengue (1); developmental delay (1); fibrosis (1); genetic disease (1); Japanese encephalitis (1); Kidney Cyst (1); lung carcinoma (1); myocardial infarction (1); Obesity (1); orofaciodigital syndrome (1); renal failure (1); Rod-cone dystrophy (1); Senior-Loken syndrome (1); short rib-polydactyly syndrome (1); type 2 diabetes (1).